TNF (tumor necrosis factor)
Diseases named in the same sentence as TNF in open-access papers (continued):
Sharing a sentence is not in itself a finding about the gene and the disease.
type 2 diabetes (continued). "Nowadays PCOS is considered a low grade chronic inflammation state, with high serum levels of tumor necrosis factor - α (TNF-α), interleukin-6 and CRP, that could be the link between PCOS and its long-term complications like type 2 diabetes and cardiovascular disease." (PMID 30850700, 2019). "Our results revealed that the levels of TNF-α, IL-6, and MCP-1 were observably decreased after the administration of JQJT tablets, which indicated that JQJT tablets could inhibit the inflammatory reaction in type 2 diabetes." (PMID 30733971, 2019). "However, our previous works found that inhibition of arginase activity by ABH and knockout arginase 1 in endothelial cells effectively alleviated the enhancement of ROS and vascular inflammation in type 2 diabetes mice model, but TNF-α was not involved." (PMID 30319431, 2018). "Furthermore, they evaluated the protective effects of flavone, fisetin, morin, or tricetin on expression of pro-inflammatory cytokines, such as IL-6 and TNF-α, using an ex vivo system after procurement of blood samples from healthy men and patients with COPD and type 2 diabetes (T2D)." (PMID 28974953, 2017). "Interestingly, anthocyanin (e.g., cyanidin-3-O-glucoside) have been shown to downregulate the RBP4 in the white adipose tissue in type 2 diabetic mice while at the same time upregulating the GLUT-4 and suppressed adipocytokines (monocyte chemoattractant protein-1 and tumor necrosis factor-α)." (PMID 29023424, 2017). "Thus, NONRATT021972 siRNA treatment may block P2X7 activation in the DRG to inhibit the up-regulation of TNF-α and GFAP and to decrease the pain behaviors of type 2 diabetic rats." (PMID 27107575, 2016). "Proinflammatory cytokines, such as tumor necrosis factor alpha (TNF-α) and IL-6, generated during the innate response, can inhibit insulin signaling through the phosphorylation of insulin receptor substrate 1 (IRS-1), serving to link inflammation with IR and type 2 diabetes." (PMID 26458065, 2015). "Studies analyzing the association between serum TNF-α and DXA scans have not been reported in cSLE so far, but studies on healthy women and type-2 diabetes patients showed an association between plasma levels of TNF-α and visceral adipose tissue volume measured by CT-scan." (PMID 24741576, 2014). "Therefore, we performed a prospective observational study to investigate the relationship between different biomarkers and to determine the role of urinary TNF-α and NGAL as predictors of a decline in the estimated glomerular filtration rate (eGFR) in patients with type 2 diabetes." (PMID 24250725, 2013). "So possibly in patients with type 2 diabetes, leptin and TNF-α status can not be explained by the ‘‘cytokine–leptin hypothesis’’." (PMID 24260344, 2013). "However, the infusion of TNF-α-neutralizing antibodies into obese, insulin-resistant subjects, or type 2 diabetic patients, did not improve insulin sensitivity." (PMID 22110480, 2012). "Additionally, a negative correlation has been reported between PGC-1α and TNFα mRNA levels in SkM of type 2 diabetes patients independent of BMI." (PMID 22384185, 2012). "Indeed, for example, although TNF-α is required for DCs generation from CD34 + precursors, its increased production by monocytes in type 2 diabetes with CAD may adversely affect blood DC differentiation from CD34 + precursors." (PMID 21658276, 2011). "In addition, a significant increase in Gram-negative bacteria is also found in type 2 diabetes and CKD patients, which contain LPS in the outer membrane and are associated with the elevation of inflammatory biomarkers such as TNF-α, IL-6, and C-reactive protein (CRP) in fecal microbiota samples." (PMID 37362429, 2023). "However, the tendency to an increased level of basal TNF secretion by monocytes from patients with type 2 diabetes without DFS may reflect an increased pro-inflammatory activity of monocytes, which may contribute to the gradual formation of a peptic ulcer." (PMID 31877847, 2019).
type 2 diabetes (continued). "The involvement of tumor necrosis factor (TNF)-related biomarkers [TNFα, progranulin (PGRN), TNF receptors (TNFR1 and TNFR2)] and uric acid (UA) in renal function decline was investigated in patients with type 2 diabetes (T2D)." (PMID 30333553, 2018). "In the current study, where all women had a history of GDM, those who developed IGT or type 2 diabetes had higher CRP levels, but TNFα, TNFR1, IL-6, and SAA were not significantly different between groups." (PMID 29951553, 2018). "Baseline levels of urinary TNF-α and NGAL were measured in 63 non-diabetic controls and 201 patients with type 2 diabetes and different albuminuria statuses." (PMID 24250725, 2013). "However, the moderate coma cases showed no significant increase in CSF IFN-γ, TNF-α or TGF-β in relation to mild or no coma cases." (PMID 23145191, 2012). "Finally, clinical studies with pomegranate seed oil in type 2 diabetic patients have resulted in reductions in the levels of fasting blood sugar, interleukin-6 and TNF-α (tumor necrosis factor-α); however, no significant changes have been observed in insulin and lipid profiles." (PMID 31979390, 2020).
asthma (917 papers, 2004 to 2026). "Together, these data indicate that systemic IL-4, IL-9, and TNF-α skewing characterizes T2-high asthma overall, while non-T2 pediatric asthma is marked by elevated Th1/Th17-associated and pro-inflammatory cytokines that are largely absent in adults." (PMID 41601686, 2026). "Several studies have shown a link between the 308-G/A polymorphism in the TNF-alpha gene and both asthma and obesity." (PMID 40426941, 2025). "This asthma‐associated composition furthermore correlated with lower levels of topical pro‐inflammatory airway immune mediators (IL‐1β and TNF‐α) and higher levels of monocyte and T‐cell recruiting chemoattractants (CCL‐2 and CCL‐17)." (PMID 39840649, 2025). "in germ‐free murine models markedly reduced levels of pro‐inflammatory cytokines associated with severe asthma (IL‐17A, IL‐6, TNF‐α)." (PMID 41310922, 2025). "Neutrophilic asthma related to smoking or post-viral inflammation, and obesity-associated asthma, which are associated with T helper type 17 and type 1 cytokines such as interferon γ, TNFα, and IL-17." (PMID 41318536, 2025). "In particular, IL-6 and TNF-α are deeply associated with asthma severity, such as airway remodeling and fibrosis in the late stage." (PMID 40323927, 2025). "These modules included networks related to IL-17, TNF, and inflammasome signaling, all of which have been implicated in non-T2 or “neutrophilic” asthma endotypes." (PMID 41279354, 2025). "The NcoI variant in the lymphotoxin-A gene (LTA, located at 6p21.3), which interacts with the TNF 308-G/A polymorphism, has been connected to various asthma-related traits, including atopic asthma." (PMID 40426941, 2025). "The severity of the disease was notably associated with pro‐inflammatory cytokines such as TNF‐α and IL‐5, adding to the growing evidence that asthma cannot be understood through a single phenotypic lens." (PMID 41159221, 2025). "If, in the future, studies are designed to specifically evaluate the efficacy of etanercept in obese asthma, caution must be taken since anti-TNF-α therapy is associated with statistically significant weight gain." (PMID 38878250, 2024). "The sensitised mice exhibited an increased expression of the Th2-like and asthma-associated cytokines, IL-4, IL-5, and IL-13, as well as mRNA encoding for pro-inflammatory TNF-α and the Th1 cytokine IFN-γ." (PMID 38765484, 2024). "It has been reported that TNF-α induces a significant inflammatory response in human ASMCs, including the upregulation of chemokines and cytokines linked to asthma and the activation of the signaling pathways associated with inflammation and remodeling." (PMID 39337534, 2024). "Levels of tumor necrosis factor alpha (TNF-α) have been linked to inflammatory respiratory disorders, which include asthma, chronic obstructive pulmonary disease, and sarcoidosis." (PMID 39204109, 2024). "Of the various pulmonary diseases, TNF-α is implicated in asthma, chronic bronchitis, chronic obstructive pulmonary disease, acute lung injury, and acute respiratory distress syndrome." (PMID 39272983, 2024). "TNF-α is produced by a variety of pro-inflammatory cells and structural cells during the pathogenesis of asthma, and TNF-α is mainly associated with the Th1 response." (PMID 38218943, 2024). "Histamine, protease enzymes, tumor necrosis factor (TNFα), prostaglandins (PGs), leukotrienes (LTs), and interleukins (ILs) are among the chemical mediators implicated in asthma." (PMID 38348340, 2024). "In contrast, Th2-low asthma is mediated by IL-17 and associated with IL-6, which is related to Th17 differentiation and therefore IL-17 secretion, and TNFα." (PMID 39239645, 2024). "The rs1799964 variant in the regulatory region of TNF-α (Tumor Necrosis Factor α) has previously been associated with severe or difficult asthma." (PMID 39766875, 2024).
asthma (continued). "Asthma was associated with the increased expression of pro-inflammatory cytokines, including IL-2, IL-5, IL-13, IL-17A, IL-22, IL-33, and TNF-α, and reduced levels of anti-inflammatory cytokine, IL-10 and adipokine, leptin in the circulation." (PMID 39902293, 2024). "Immune and inflammatory pathways (eg, IL-2, TNF-α, NF-κB, and C/EBPs) underlie microbiome-epigenetic associations with asthma treatment, representing potential therapeutic pathways to be targeted." (PMID 38906272, 2024). "TNF-α is associated with the onset of asthma, a long-term inflammatory lung disease characterized by bronchoconstriction, airway inflammation, and increased airway sensitivity." (PMID 39407835, 2024). "Asthma is a heterogeneous airway inflammatory disease associated with inflammation driven by T helper 2 cell (Th2) cytokines and non-Th2, TNF-α-mediated inflammation." (PMID 39459639, 2024). "This endotoxemia triggers the activation of the nuclear factor-κB (NF-κB) pathway and upregulates the expression of IL-6 and TNF-α, thereby exacerbating inflammation associated with asthma." (PMID 39411430, 2024). "The interaction of cytokines such as interleukin (IL)-4, transforming growth factor-beta 1 (TGF-β1), tumor necrosis factor-alpha (TNF-α), and IL-17 are also implicated in asthma pathogenesis." (PMID 38731707, 2024). "It is also implicated in ECM deposition and is upregulated by TNF-α, highlighting its significance in the inflammatory and structural changes characteristic of asthma." (PMID 39337534, 2024). "The results indicated that the use of mesenchymal stromal cells associated with the reduction of interleukin 17, TNF-α, β1 and had a long-term positive effect on severe asthma in horses." (PMID 38178929, 2024). "Tumor necrosis factor-alpha (TNF-α) was reported to be associated with steroid-resistant asthma and asthma exacerbation frequency." (PMID 37208441, 2023). "A large-scale meta-analysis supports a strong association between the TNF-α gene promoter polymorphism (−308G/A) and the development to asthma in both children and adults." (PMID 36911417, 2023). "Th17 cells produce IL-17A, IL-17F, IL-21, IL-22, and TNF-α to perform their functions, and IL-17A and IL-17F are linked to severe asthma with neutrophil inflammation and responsible for corticosteroid resistance in asthma." (PMID 38203353, 2023). "TNF-α is one of the earliest cytokines produced in response to endotoxins, and it is of basic proteins associated with asthma in various populations." (PMID 37629528, 2023). "In a latest report, tumor necrosis factor alpha gene (TNF-α)-308G/A polymorphism in asthma patients was found to be associated with their metabolic profile." (PMID 36911417, 2023). "To determine the effects of IL-31 on the expression of asthma-associated genes, we quantified the expression of genes associated with inflammation (IFNγ, TNF-α, IL-6, and IL-17) and Th2 responses (IL-4, IL-13, ARG1, MUC4, and MUC5AC)." (PMID 38081868, 2023). "Airway inflammation and pro-inflammatory cytokines such as tumor necrosis factor alpha (TNFα) underlie the pathophysiology of respiratory diseases, including asthma." (PMID 37958799, 2023). "In a follow up report, pulmonary inflammation models (LPS lavage and asthma) were developed to test siRNA or plasmid DNA (encoding a small hairpin RNA) against TNF-alpha." (PMID 37298407, 2023). "Other cytokines, IL-21 activate Th17 in an autocrine manner, while TNF-α is associated with airway inflammation in severe asthma." (PMID 37377958, 2023). "We also studied the associations between this variant and serum levels of some asthma biomarkers (IgE, TNF-α, TGF-β1) and the clinical manifestations of the disease." (PMID 36344553, 2022). "Although the underlying mechanism is still unclear, numerous studies have reported that TNF-α is highly linked to different types of inflammatory lung disease including pulmonary fibrosis, asthma, and chronic obstructive pulmonary disease (COPD)." (PMID 36348343, 2022).
asthma (continued). "In asthma, airway inflammation caused by tumor necrosis factor (TNF)-α, IFN-γ, IL-4, and IL-13 dysregulate epithelial barrier activities." (PMID 35625578, 2022). "The proinflammatory cytokines, TNFα and IL-13, which are heavily implicated in asthma severity, were shown to decrease SERCA2 expressions in human airway smooth muscle cells." (PMID 36685580, 2022). "Clinically, Th1 inflammation-associated cytokine, tumor necrosis factor-alpha (TNFα), has been proposed as a mainstay target of asthma therapy by depleting the contractile aspects of asthma." (PMID 35883681, 2022). "In the literature, numerous studies have found an association between polymorphisms of TNF with the susceptibility and severity of asthma, especially the polymorphism rs1800629." (PMID 35456412, 2022). "TNF and IL-6 are the two cytokines with a broad spectrum of immunodulatory effects, yet in the context of asthma they both can be defined as pathogenic." (PMID 35408882, 2022). "TNF represents an important biomarker in severe asthma and TNF gene polymorphisms are associated with increased risk of asthma development." (PMID 35408882, 2022). "Cough and asthma treatment with EH was primarily associated with anti-inflammatory activity, and the enriched signaling pathways for TNF, MAPK, and PI3K-Akt were associated with inflammation." (PMID 35807303, 2022). "On the other hand, increased JNK activity due to the up-regulation of TNF-α and other pro-inflammatory cytokines has been reported in the airways of asthmatic patients, and associated to GC resistance in severe asthma." (PMID 34576214, 2021). "For example, in acute model of asthma, administration of monoclonal anti-TNF antibodies was associated with reduced inflammatory cell infiltration, airway goblet cell metaplasia and AHR." (PMID 34084159, 2021). "TGFβ (transforming growth factor beta), IL-22, IL-6 and TNF also contribute to tissue remodeling and fibrosis that are associated with the late stages of asthma progression." (PMID 34084159, 2021). "IL-6 and TNF are key pro-inflammatory cytokines implicated in neutrophilia, extracellular matrix production and chronic inflammation during severe asthma." (PMID 34084159, 2021). "The association of tumor necrosis factor (TNF) polymorphisms with asthma and differences in susceptibility to the adverse effects of pollutants has been demonstrated." (PMID 32867076, 2020). "Again, BioPM induced cytokine production in a concentration-dependent manner by PBMCs from patients during loss of asthma control (with the exception of IFNγ and TNFα production induced by BioPM from the goat farm)." (PMID 32620109, 2020). "In a recent 11-year study in over 4 million Norwegians, an inhaled asthma medication with anti-TNF activity, a brain-penetrant drug, was associated with lower levels of t-α-syn and decreased the risk of PD." (PMID 32375873, 2020). "It has been shown that a reduced production of IFN-γ by the T cells of asthmatic patients correlates with disease severity and that TNF-α is associated with the pathogenesis of asthma." (PMID 32899766, 2020). "In patients with COPD with asthma cohort, poor lung function is associated with high levels of cytokines (e.g., tissue necrosis factor alpha [TNF-α])." (PMID 32092112, 2020). "First, inflammatory cytokines, including TNF-α and IL-6, are associated with an increased risk of asthma." (PMID 32999682, 2020). "Differential methylation patterns have been observed in three genes-androgen receptor (AR), TNFα, and IL-4 causing asthma in children." (PMID 32435260, 2020). "IFN-γ, LPS, and TNF-α activate M1 polarization, linked with Th1 cells, Th17 cells, neutrophilic asthma and severe asthma." (PMID 33013382, 2020). "Since IL-1β and TNFα are pro-inflammatory and are associated with macrophage activation and neutrophilic inflammation, their levels are increased in severe asthma and COPD." (PMID 32493287, 2020).